SH2B3 (SH2B adaptor protein 3)
Diseases named in the same sentence as SH2B3 in open-access papers (continued):
Sharing a sentence is not in itself a finding about the gene and the disease.
type 1 diabetes (26 papers, 2011 to 2025). "Variant of Lnk/SH2B3 adaptor has been reported as a risk for several autoimmune diseases, including type 1 diabetes." (PMID 41027725, 2025). "The gene SH2B3 acts as a negative regulator of cytokine signaling and cell proliferation, which is known to be associated with type 1 diabetes and celiac disease." (PMID 33835050, 2021). "SH2B3 mutations were associated with susceptibility to celiac disease type 13 and insulin-dependent diabetes mellitus." (PMID 34899825, 2021). "The broad association at the SH2B3 locus looked similar in studies of type 1 diabetes and vitiligo, giving credibility to the result, but making it challenging to appoint a single candidate gene." (PMID 33574239, 2021). "For example, rs3184504, a non-synonymous SNP located in exon 3 of SH2B3, is associated in GWAS with BP, coronary heart disease, hypothyroidism, rheumatoid arthritis, and type I diabetes." (PMID 25785607, 2015). "For example, SH2B3 regulates cytokine activity, and rs3184504 within this gene has been replicably associated with risk for type 1 diabetes and celiac disease." (PMID 22277159, 2012). "Interestingly, association between type 1 diabetes and variants in the chromosome region 12q24 that contains SH2B3 has been demonstrated." (PMID 36123612, 2022). "For example, rs3184504, a nonsynonymous SNP in SH2B3 that was associated in GWAS with BP, coronary heart disease, hypothyroidism, rheumatoid arthritis, and type 1 diabetes, is a trans-eQTL for 6 of our 34 BP signature genes from the meta-analysis (FOS, MYADM, PP1R15A, TAGAP, S100A10, and FGBP2)." (PMID 25785607, 2015). "This region, which encompasses ATXN2 and SH2B3 genes, has been previously associated with several complex diseases, such as retinal vascular caliber and chronic kidney disease, myocardial infarction or type 1 diabetes." (PMID 23844121, 2013). "This was consistent with the fact that the index SNP rs3184504, which is also a missense SNP of SH2B3, has been found to be associated with multiple phenotypes and diseases relating to blood pressure, blood cells, cholesterol levels, as well as cardiovascular diseases and type-1 diabetes." (PMID 40408443, 2025). "Apart from the HLA complex, which remains by far the strongest predictor of type 1 diabetes mellitus, the most important loci conferring susceptibility are located in the INS, PTPN22, IL2RA, SH2B3 genes." (PMID 34556755, 2021). "The overlapping loci included UBASH3A and SH2B3 in type 1 diabetes and celiac disease, and LPP in autoimmune thyroid disease and vitiligo." (PMID 33574239, 2021). "Here we found that risk variants of two genes, SH2B3 and GAB3, were more predictive of type 1 diabetes in African American subjects." (PMID 29540798, 2018). "Previous studies have linked polymorphisms in two of these genes to Type 1 diabetes (CBLB and SH2B3)." (PMID 24728409, 2014). "This is supported by a recent study which showed that variants in LD with SH2B3, BACH2, and PTPN22 are associated with TPOAb levels in patients with type 1 diabetes." (PMID 24586183, 2014). "SH2B3 also shows opposite directions of effect in multiple sclerosis and celiac compared to rheumatoid arthritis, psoriasis, type 1 diabetes, and hypothyroidism." (PMID 22493691, 2012).
celiac disease (25 papers, 2011 to 2025). An autoimmune genetic disorder with an unknown pattern of inheritance that primarily affects the digestive tract. "a possible overlap in cytokine-mediated immune responses is suggested by STAT6, which is linked to cytokine signaling in NHL, and SH2B3, which is involved in immune control in Celiac disease." (PMID 40321894, 2025). "Elevated immunological responses and heightened vulnerability to autoimmune illnesses, such as celiac disease, are linked to mutations in SH2B3." (PMID 40321894, 2025). "For example, one of the pioneering works suggested that the celiac disease rs3184504*A variant in the SH2B3 gene had adaptive history and possibly played a role in pathogen resistance." (PMID 36400766, 2022). "Our findings are thus in accordance with previous studies where the 12q24/SH2B3 locus has been associated with both coeliac disease and T1D." (PMID 33446885, 2021). "Another study in children was able to evidence the increased risk (>90%) of developing celiac disease by the genotype of five candidate genes (SH2B3, RGS1, TAGAP, cREL, and LPP)." (PMID 32365683, 2020). "In conclusion, this study reports for the first time that MMEL1 518 Met/Thr polymorphism contributes to celiac disease risk among Saudi Arabians, both in single and also in synergistic cooperation with SH2B3 gene marker." (PMID 26843707, 2015). "This evidence was further supported by results obtained in celiac disease, systemic lupus erythematosus, rheumatoid arthritis and multiple sclerosis, underscoring the pivotal role of SH2B3 in loss of immune tolerance and development of autoimmunity." (PMID 23844121, 2013). "Both MDM20 and SH2B3 are also associated with T1D, and SH2B3 is additionally associated with celiac disease and both myocardial infarction and asthma." (PMID 22046141, 2011). "A recent study on Celiac disease (CeD) revealed that the expression of SH2B3 is influenced by the methylation and it is reported that hypomethylation is associated with higher expression of the genes in CeD patients than controls." (PMID 35246549, 2022). "As regards coeliac disease diagnosis above 7 years of age in the case–control analysis, rs653178 (at SH2B3/ATXN2), rs13010713 (at ITGA4/UBE2E3), rs13151961 (at IL2/IL21), rs11712165 (at CD80) and rs10936599 (at MYNN) showed an association." (PMID 33446885, 2021). "SH2B3 is also important in the mechanism of celiac disease by inflecting the immune response to gut bacteria." (PMID 34948375, 2021). "Although allele and genotype frequencies of IRAK1 and SH2B3 were insignificantly different between patients and controls, a potential synergistic effect was seen between MMEL1 and SH2B3 genes, reinforcing the significance of MMEL1 in celiac disease susceptibility." (PMID 26843707, 2015). "Replicated associations that were genome-wide significant in their own right in FinnGen (class 1) included for instance that between rs10774625 (nearest gene: SH2B3/ATXN2) and coeliac disease (p = 1.3×10−6 in UK Biobank; p = 2.1×10−10 in FinnGen)." (PMID 40493586, 2025). "Replicated associations included for instance that between rs10774625 (nearest gene: SH2B3/ATXN2) and coeliac disease, and that between rs12350420 (nearest gene: MVB12B) and glaucoma." (PMID 40493586, 2025). "Our current results place the candidate genes SH2B3, CTLA4, BACH2 and UBASH3A at the very heart of the immune response in the pathogenesis of both T1D and celiac disease." (PMID 21829393, 2011). "Lastly, four of the nine TPOA associated SNPs (in SH2B3, CTLA4, BACH2 and UBASH3A) have also been associated with celiac disease (but not the SNPs in RASGRP1, STAT4, PTPN22, IL2 and FCRL3)." (PMID 21829393, 2011). "We replicate the association between rs3184504 (mapped to SH2B3/ATXN2), previously shown to be associated with celiac disease, in our extreme longevity phenotype, but not the other three variants (although they are associated with continuous parent's age at death p<0.05)." (PMID 27015805, 2016).
myeloproliferative neoplasm (19 papers, 2018 to 2026). A clonal hematopoietic stem cell disorder, characterized by proliferation in the bone marrow of one or more of the myeloid (i.e., granulocytic, erythroid, megakaryocytic, and mast cell) lineages. "Somatic mutations in SH2B3 gene have been described in myeloproliferative neoplasms, while germline SH2B3 pathogenic variants have been reported in myelodysplastic syndromes and acute lymphoblastic leukemia." (PMID 36123612, 2022). "SH2B3 somatic mutations have been reported in myeloproliferative neoplasms such as primary myelofibrosis." (PMID 32641076, 2020). "Application of a next-generation sequencing (NGS) approach targeted for myeloid malignancies confirmed wild-type JAK2 exons 12–15 and identified a common SH2B3 W262R single-nucleotide polymorphism associated with the development of hematological features of myeloproliferative neoplasms (MPNs)." (PMID 29682367, 2018). "This study retrospectively analyzed the clinical data of the first reported case in China of myeloproliferative neoplasm (MPN) driven by a homozygous germline SH2B3 mutation, aiming to deepen the understanding of this rare MPN subtype." (PMID 42161666, 2026). "In hematological conditions somatic SH2B3 variants have been described in 5–7% of patients with myeloproliferative neoplasms (MPN) and, at lower frequency, in juvenile myelomonocytic leukemia (JMML), high-risk B- and early T-cell precursor acute lymphoblastic leukemia (ALL)." (PMID 40481232, 2025). "On the contrary, previous studies show that SH2B3 promotes Jak/STAT signaling in myeloproliferative neoplasms and promotes ovarian cancer, breast cancer, and anaplastic thyroid carcinoma progression." (PMID 33937225, 2021). "By accelerating STAT3 phosphorylation and increasing NOTCH-1 signaling, loss-of-function variants in SH2B3 have been linked to the oncogenesis of myeloproliferative neoplasms (MPN), early T-ALL, Ph-like ALL, B-ALL, and non-malignant hematological disorders." (PMID 36834692, 2023). "SH2B3 is mutated in 5–7% of myeloproliferative disorders, lymphoid leukemia and the non-malignant disease idiopathic erythrocytosis." (PMID 32098966, 2020). "Loss-of-function mutations in SH2B3 are reported to play an important role in the oncogenesis of myeloproliferative neoplasms (MPN), early T-ALL, Ph-like ALL, B-ALL and nonmalignant hematological diseases by accelerating STAT3 phosphorylation and increased NOTCH-1 signaling." (PMID 32085659, 2020). "Variant c.901G>A (NM_005475.2) in SH2B3 gene was the only one already identified in the erythrocytosis patient without myeloproliferative neoplasm (MPN)." (PMID 34349782, 2021).
leukemia (17 papers, 2015 to 2024). A malignant (clonal) hematologic disorder, involving hematopoietic stem cells and characterized by the presence of primitive or atypical myeloid or lymphoid cells in the bone marrow and the blood. "In leukemias, the enrichment of SH2B3 aberrations may indicate that the loss of SH2B3 contributes to the disease progression and increases the sensitivity of leukemias to Tyrosine kinase inhibitors." (PMID 36059531, 2022). "SH2B3 encodes a lymphocyte adaptor, reported as a tumor suppressor gene in leukemia." (PMID 33428680, 2021). "Our data implicate Ikaros/IL7R/SH2B3 signaling in oncogenesis of high-risk leukemia." (PMID 27322554, 2016). "Loss of SH2B3 results in an increase in Janus kinase-signal transduction, activation of transcription signaling and lymphoid cell proliferation, which further promotes leukemia development in a mouse model of NOTCH1-induced ALL." (PMID 27322554, 2016). "Furthermore, the circRNA-miRNA-mRNA interaction network of hsa_circ_0004277 from cytoscape analysis offered us several downstream gene-candidates, among which SH3GL2 and PPARGC1A were reported to be involved in several solid tumors, and SH2B3 especially as “a new leukemia predisposition gene”." (PMID 28282919, 2017). "According to previous literature studies, SH2B3 and ASXL1 mutations are associated with poor prognosis of MPN patients, such as low overall survival (OS), progression of MF and leukemia transformation." (PMID 38618943, 2024). "SH2B3 is known as a tumor suppressor in leukemia, supporting the relevancy of this gene to clinical benefit." (PMID 33428680, 2021). "Homology modelling of a leukaemia-associated SH2 domain mutation and in vitro analysis of patient-derived xenograft cells implicated the JAK/STAT pathway as one likely target for SH2B3 tumour suppressor activity in iAMP21-ALL." (PMID 30816328, 2019). "Somatic SH2B3 mutations have also been identified in 3% of ALL, suggesting that SH2B3 loss plays a role in initiation and progression of human leukaemia through dysregulated cytokine signalling." (PMID 26553438, 2015). "While SH2B3 suppresses IL-7R/JAK/STAT signaling to restrict pro-/pre-B progenitor expansion and leukemia development, Ikaros plays an essential role in lymphocyte development and functions as a tumor suppressor in leukemia." (PMID 27322554, 2016).
diabetes (14 papers, 2016 to 2025). "SH2B3 was associated with diseases like atherosclerosis and thrombosis, cancers, diabetes, etc95–97." (PMID 35246549, 2022). "We used a missense polymorphism (R262W, SNP rs3184504) in the SH2B adaptor protein 3 (SH2B3) gene to examine the effect of leukocyte count on diabetes." (PMID 26891449, 2016). "These include CCND2, CILP2, PBX4, SH2B3, SLC6A4, TCF7 and KLF14, which have polymorphisms associated with diabetes risk." (PMID 27029739, 2016). "A missense variant R262W in the SH2B3 (SH2B adaptor protein 3) gene, coding for a protein that negatively regulates hematopoietic cell proliferation, was also studied in relation to incidence of diabetes." (PMID 26891449, 2016). "However, a missense polymorphism in the SH2B3 gene, strongly associated with leukocyte count, was not related to glucose, HbA1c or incidence of diabetes." (PMID 26891449, 2016). "For the first time, through a mediation analysis, we provide evidence that links Cd exposure to the SH2B3-β2M pathway of blood pressure homeostasis in people with and without diabetes." (PMID 41009768, 2025).
acute lymphoblastic leukemia (13 papers, 2016 to 2025). Leukemia with an acute onset, characterized by the presence of lymphoblasts in the bone marrow and the peripheral blood. "SH2B3 (regulates integrin signaling in endothelial cells) and TCF12 (control of lymphoid differentiation) have been linked to acute lymphocytic leukemia." (PMID 27959900, 2016). "LNK (SH2B3) is an adaptor protein studied extensively in normal and malignant hematopoietic cells, which plays an important role in Multiple blood diseases, such as Fanconi anemia (FA), Acute lymphoblastic leukemia (ALL), Aortic dissection (AD) and so on." (PMID 32322171, 2020). "SH2B3 is a negative regulator of several key tyrosine kinases and cytokines, particularly JAK-STAT signaling, and has known tumor suppressor function in acute lymphoblastic leukemia and lung cancer." (PMID 40428397, 2025).
coronary artery disease (12 papers, 2013 to 2025). "In this context, mutations of SH2B3/LNK were present in all patients with a majority of responders expressing the exon variant RS3184504 that is associated to coronary artery disease and increased thrombocyte count." (PMID 32629392, 2020). "Examples include the association of the APOE/TOMM40 locus with pancreatic cancer and total cholesterol levels, the association of the ABO locus with macular degeneration and coronary artery disease, and the association of the SH2B3/ATXN2 locus with diastolic blood pressure and rheumatoid arthritis." (PMID 26677855, 2015). "In genome wide association studies (GWAS) of cardiovascular patients, the SH2B3 phosphorylation related missense variant rs3184504 was found to be associated with increased platelet count, monocyte proliferation, hypertension, peripheral/coronary artery disease, autoimmune disease, and longevity." (PMID 32629392, 2020). "Here, the authors show shared genetic loci between leukocyte telomere length and coronary artery disease, highlighting genes such as SH2B3 and pathways involved in DNA biosynthesis and telomere maintenance." (PMID 41027922, 2025). "At present, the regulatory role of SH2B3 in stem cell proliferation and inflammation response remains unclear in patients with coronary artery disease, especially in post-myocardial infarction repair leading either to regeneration or inflammatory fibrosis of the myocardium." (PMID 32629392, 2020). "The adaptor protein Src homology 2-B3 (SH2B3), also known as LNK, is a key regulator in heart diseases including coronary heart disease, peripheral artery disease, and hypertrophy." (PMID 35692373, 2022).
myocardial infarction (12 papers, 2011 to 2025). Gross necrosis of the myocardium, as a result of interruption of the blood supply to the area, as in coronary thrombosis. "The strongest association was with rs3184504, a missense variant in a known inflammatory gene, SH2B3, and has been associated with multiple phenotypes including myocardial infarction and hypertension." (PMID 34341450, 2021). "Only the SH2B3 SNP rs3184504 was associated with incident myocardial infarction (315 events), with each minor allele increasing the risk (P = 0.011; OR 1.23 95% CI 1.05–1.43)." (PMID 21533024, 2011). "Given the known association of sICAM-1 with cardiovascular risk and the association of selected SNPs with sICAM-1, we estimated the power to detect an association between the SH2B3 SNP rs3184504 and myocardial infarction to be 6%, for alpha = 0.05." (PMID 21533024, 2011). "In a rat myocardial infarction model, however, knockout of Sh2b3/Lnk led to significantly increased fibrosis and leucocyte infiltration, resulting in reduced cardiac function." (PMID 27189168, 2016). "Temporary downregulation of adaptor gene SH2B3 in cKIT-CD117+/CD133+/CD34+ HSC can be a therapeutic switch to improve downregulated stem cell response in ischemia, tissue repair, and myocardial infarction." (PMID 32629392, 2020).
rheumatoid arthritis (12 papers, 2012 to 2025). A chronic, systemic autoimmune disorder characterized by inflammation in the synovial membranes and articular surfaces. "Other loci containing alleles robustly associated with higher eosinophil count and increased risk of rheumatoid arthritis were COG6, SPRED2, RUNX1, and the highly pleiotropic ATXN2/SH2B3/BRAP region." (PMID 27863252, 2016). "In addition, SH2B3 was reported to regulate cytokine production via the Janus Kinase (JAK)- signal transducer and activator of transcription (STAT) pathway, which is shown to have important immune-regulatory functions in rheumatoid arthritis (RA) and axSpA." (PMID 36844956, 2022). "CD, type I diabetes (T1D), and rheumatoid arthritis (RA) share the HLA region, and other non-HLA regions, including IL2-IL21, SH2B3, and TAGAP regions." (PMID 23008734, 2012).